BDNF (brain derived neurotrophic factor)
Diseases named in the same sentence as BDNF in open-access papers (continued):
Sharing a sentence is not in itself a finding about the gene and the disease.
multiple sclerosis (96 papers, 2010 to 2025). A progressive autoimmune disorder affecting the central nervous system resulting in demyelination. "The BDNF Val66Met polymorphism is known to reduce BDNF expression and secretion; its role in multiple sclerosis (MS) is poorly investigated." (PMID 33815257, 2021). "Brain-Derived Neurotrophic Factor (BDNF) and its most common polymorphism Val66Met are known to have a role in Multiple Sclerosis (MS) pathogenesis." (PMID 30352103, 2018). "Higher secretion of BDNF in multiple sclerosis patients has been linked with higher WM volume, as well as higher inflammatory activity, suggesting protective up-regulation." (PMID 26477656, 2016). "We also observed an association between Rey AVLT scores and the BDNF SNP rs2030324 which has previously been associated with cognitive processes in healthy aging and multiple sclerosis." (PMID 26708060, 2016). "In addition, BDNF plays a central neuroprotective role by opposing damage caused by ischemia, traumatic injury, multiple sclerosis, heavy metal intoxication, and aging." (PMID 32131481, 2020). "We thus studied how the Brain Derived Neurotrophic Factor Val66Met genotype, a common polymorphism influencing the hippocampal function in healthy controls, impacted on brain networks underlying episodic memory in patients with Multiple Sclerosis." (PMID 23593393, 2013). "BDNF often promotes IL-10 release, as demonstrated in multiple sclerosis studies, indicating a protective feedback mechanism." (PMID 41511349, 2025). "On the other hand, exercise also promotes the increase of brain-derived neurotrophic factor (BDNF) in people with multiple sclerosis." (PMID 41019298, 2025). "In the literature, recent meta-analysis studies indicated that peripheral BDNF concentrations significantly increased after exercise intervention in healthy individuals, older adults, individuals with multiple sclerosis, and neurodegenerative disorders." (PMID 38785805, 2024). "Further studies with larger cohorts and longitudinal follow-ups are needed to improve our understanding of the effects of BDNF in the central nervous system, especially in the context of multiple sclerosis." (PMID 39148705, 2024). "In the experimental autoimmune encephalomyelitis (EAE) model of multiple sclerosis, astrocyte-specific BDNF knockout led to more severe clinical course with increased axonal injury and loss." (PMID 38254691, 2024). "To date, studies assessing the role of BDNF in patients with multiple sclerosis remain inconclusive." (PMID 39148705, 2024). "Accordingly, this review aimed to analyse the current literature regarding BDNF in different areas of multiple sclerosis and to provide an overview of the current state of knowledge in this field." (PMID 39148705, 2024). "This review examines the controversial BDNF levels in multiple sclerosis (MS) stages and explores how BDNF signaling and its modulators influence MS pathogenesis and outcomes." (PMID 39654365, 2024). "The levels of urine NGF/Cr and BDNF/Cr were associated with the etiology of NLUTD, and were found to be elevated in multiple sclerosis patients when compared to SCI and spina bifida patients." (PMID 36766573, 2023). "Reports on the alterations of the BDNF levels in patients with multiple sclerosis (PwMS) are controversial, but overall, BDNF is usually increased during relapse, with normal levels during remission phases." (PMID 35239684, 2022). "Since several already marketed drugs are able to modulate BDNF levels, these results pave the way to the possibility of repositioning these drugs in multiple sclerosis." (PMID 33259004, 2022). "Since several already marketed drugs are able to modulate BDNF levels, the possibility of drug repositioning for multiple sclerosis should be addressed in future studies." (PMID 33259004, 2022).
multiple sclerosis (continued). "Glatiramer acetate, originally adopted to treat multiple sclerosis, can enhance central brain-derived neurotrophic factor (BDNF) activity and enhance neurogenesis, helping to resolve BDNF deficiency in PD." (PMID 35897954, 2022). "Aerobic exercise activity conducted for more than 3 months by subjects with MS and volunteers showed an increase in hippocampal volume, and physical activity has been shown as well to increase BDNF concentrations in subjects with multiple sclerosis." (PMID 35911894, 2022). "The BDNF gene expression in patients with multiple sclerosis showed a 2-fold decrease compared to the control group (p < 0.005)." (PMID 34202956, 2021). "Patients with multiple sclerosis showed a lower level of BDNF gene expression in PBMCs than that in the healthy group." (PMID 34202956, 2021). "In particular, immune cells from patients with RR multiple sclerosis secrete low levels of brain-derived neurotrophic factor (BDNF) and IFN-β therapy increased BDNF levels." (PMID 29655371, 2018). "Evidence suggests that low BDNF is correlated with high IL-6 in the cognitive dysfunction of multiple sclerosis patients." (PMID 25525451, 2014). "For example, in a model of multiple sclerosis, it is demonstrated that BDNF decreases TNF-α expression and upregulates IL-10 expression, an anti-inflammatory cytokine." (PMID 23912236, 2013). "Evidence from an animal study on multiple sclerosis demonstrates that BDNF decreases the expression of TNF-α." (PMID 23912236, 2013). "However, there is a major controversy concerning BDNF levels in the different stages of multiple sclerosis (MS)." (PMID 39654365, 2024). "However, there is emerging evidence for a beneficial effect of BDNF in multiple sclerosis, as studies reporting positive effects on clinical as well as MRI characteristics outweighed studies assuming detrimental effects of BDNF." (PMID 39148705, 2024). "In addition, Brain-derived neurotrophic factor (BDNF) is a key regulator of neuroprotection, neuroplasticity, and remyelination, processes that are critically important in the context of multiple sclerosis (MS)." (PMID 39935805, 2024). "Moreover, the combination of these cannabinoids decreased the expression of TNF-α and increased Brain-derived neurotrophic factor in multiple sclerosis in vivo model." (PMID 37147420, 2023). "Similarly, IFN-β-1b therapy was reported to increase BDNF production in multiple sclerosis patients." (PMID 35249177, 2022). "However, in an animal model of multiple sclerosis, BDNF promotes IL-10 that reduces clinical severity." (PMID 34109176, 2021). "In the immune systems, human T cells, B cells, and monocytes were able to produce BDNF upon activation), and BDNF has been shown to involve in the pathogenesis of experimental autoimmune encephalomyelitis and multiple sclerosis through regulating the survival of autoreactive T cells." (PMID 33673283, 2021). "Moreover, BDNF immunoreactivity was also identified in inflammatory infiltrates in brain from patients with acute disseminated encephalitis and multiple sclerosis." (PMID 31616373, 2019). "The human gene BDNF genotyping 196G/G carriers can increase the risk of multiple sclerosis only in females, but not in males." (PMID 23663500, 2013). "Likewise, in multiple sclerosis and rheumatoid arthritis, a decrease in serum BDNF levels occurs with clinical improvement, independently of other inflammatory markers." (PMID 24223945, 2013). "Moreover, the BDNF serum level is dysregulated in multiple sclerosis (MS)." (PMID 39654365, 2024). "Here, we report a brief overview on brain neurotrophic factor (BDNF)–tropomyosin receptor kinase (Trk) pathway, describing its numerous roles in the maintenance of central nervous system (CNS) health, as well as its implication in the pathogenesis of multiple sclerosis (MS)." (PMID 35911894, 2022).
multiple sclerosis (continued). "Here, we focus our attention on brain neurotrophic factor (BDNF)–tropomyosin receptor kinase (Trk) pathway, describing its multiple roles in the maintenance of central nervous system (CNS) health, as well as its implication in the pathogenesis of multiple sclerosis (MS)." (PMID 35911894, 2022). "Drugs that increase the levels of BDNF such as glatiramer acetate, known as a multiple sclerosis immune modulator, could be used to recover neuronal function by stimulating the serotonin receptor 7 in conjunction with inhibiting PTP1B, which blocks the TRKB receptor of BDNF." (PMID 34690674, 2021). "Moreover, BDNF has been implicated as an important factor associated with white matter volume in patients with multiple sclerosis independent of BDNF Val66Met (rs6265) genotype." (PMID 22523577, 2012). "Through the CREB/BDNF axis, Sem increases remyelination and overcomes demyelination, therefore can amend experimental autoimmune encephalomyelitis (EAE)-induced multiple sclerosis in mice." (PMID 40088335, 2025). "Interestingly, we showed that the severity and progression of multiple sclerosis (MS) were not influenced by the CSF levels of miR-142-3p in patients with BDNF Met66-allele background, whereas Val/Val patients with high levels of miR-142-3p exhibited a more severe phenotype." (PMID 38791290, 2024). "Patients suffering from multiple sclerosis had significantly higher levels of urinary NGF/Cr and BDNF/Cr compared to the other two groups (8 pg/mL vs. 0.56 pg/mL vs. 1.25 pg/mg; p = 0.001; and 88.3 pg/mL vs. 5 pg/mL vs. 4.8 pg/mg; p < 0.0001; respectively)." (PMID 36766573, 2023). "In our study, we assessed the effect of miRNAs on the expression level of neuropro-tective proteins, including neurotrophins (BDNF and NT4/5), heat shock proteins (Hsp70 and HSP27), and SIRT1 in the development of multiple sclerosis." (PMID 34202956, 2021). "We checked the expression level of genes, BDNF, NT4/5, HSP70, HSP27, and SIRT1 in PBMCs in patients with multiple sclerosis (patients with mild to moderate disability) and in the control group, healthy adults." (PMID 34202956, 2021). "The aim of this study was to find a link between neurotrophins (BDNF and NT4), SIRT1, heat shock proteins (HSP27 and HSP27), and miRNAs that are involved in the development of multiple sclerosis." (PMID 34202956, 2021). "BDNF downregulates the expression of TNF-α and upregulates the expression of IL10 in the model of multiple sclerosis." (PMID 21490702, 2010). "The present study aimed to evaluate the influence of omega‐3 fatty acids supplementation on the serum levels of brain‐derived neurotrophic factor (BDNF), high‐sensitivity C‐reactive protein (hs‐CRP), physical activity, and chronic fatigue in patients with multiple sclerosis (MS)." (PMID 40905016, 2025). "BDNF-secreting T cells are reduced in untreated multiple sclerosis patients and increased after interferon beta treatment, while NGF, NT-3 and NT-4 production by PBMCs in multiple sclerosis patients is enhanced in the post-relapse phase." (PMID 24223945, 2013). "(HRV): heart rate variability; (MS): multiple sclerosis; (MI): myocardial infarction; (CNS): central nervous system; (ECG): electrocardiogram; (NSM): neurogenic stunned myocardium; (TC): takotsubo cardiomyopathy; (BNP): brain natriuretic peptide; (BDNF): brain-derived neurotrophic factor." (PMID 40943142, 2025). "Exercise training may affect the blood levels of brain-derived neurotrophic factor (BDNF), but meta-analyses have not yet been performed comparing pre- and post-intervention BDNF concentrations in patients with multiple sclerosis (PwMS)." (PMID 35239684, 2022). "In addition, brain-derived neurotrophic factor (BDNF) has a neuroprotective role in experimental autoimmune encephalomyelitis and multiple sclerosis, which may have important implications for the corresponding therapies." (PMID 27642302, 2016).
injury (87 papers, 2010 to 2025). Damage inflicted on the body as the direct or indirect result of an external force, with or without disruption of structural continuity. "Overall, this study provides experimental evidence for the impact of visual stimulation on epileptic susceptibility in neonatal hypoglycemic brain injury rats and offers preliminary insights into the role of BDNF and SYN in this process." (PMID 40589985, 2025). "Additional studies are needed to better understand the mechanisms underlying BDNF reduction after severe brain injury, to aid identification of the best rehabilitative strategies to promote restorative plastic changes and recovery in patients with DOCs." (PMID 32565776, 2020). "In humans genetic polymorphisms in the BDNF gene are associated with differences in cognitive outcome after head trauma, both at early timepoints (1 month) and at later timepoints (10–15 years)." (PMID 31998207, 2019). "Activated M1 phenotype microglia produce proinflammatory cytokines such as TNF-α, IL-1β, and IL-6; M2 phenotype microglia produce brain-derived neurotrophic factor and IL-10, which has been associated with neuroprotection after brain injury." (PMID 28529954, 2017). "We previously showed that MSSI sex-dependently induced emotional dysfunction after nerve injury, which was associated with sex differences in the stress-induced regulation of BDNF expression." (PMID 28701953, 2017). "Our findings suggest the possibility that MBP and BDNF work in concert to protect against or enhance recovery from brain injury, mediating the risk of long-term mechanical and psychological injury." (PMID 26251769, 2015). "Lower BDNF levels are associated with a decline in neuroprotection, and administration of BDNF has been shown to be protective in acute brain injury and infection models." (PMID 24603727, 2014). "One hypothesized mechanism for psychedelics' beneficial effect on neuroplasticity in brain injury is via Brain-derived neurotrophic factor (BDNF), which is well-known to be implicated in both neuritogenesis and spinogenesis." (PMID 34393973, 2021). "A missense mutation in BDNF was shown to alter cognitive performance post-traumatic brain injury." (PMID 29179434, 2017). "A study found that XFZYD could reverse the reduction of BDNF and TrkB in the hippocampus caused by traumatic brain injury and increase the number of synaptic connections, as well as the expression of synaptic-related protein PSD95, axon-related protein GAP43, and neuron-specific protein TUBB3." (PMID 40430532, 2025). "BDNF is an important neurotrophic factor that primarily functions to promote neuronal survival, enhance synaptic plasticity, and thus facilitate nerve injury recovery." (PMID 40917657, 2025). "Schwan cells produce and release several mediators including BDNF, chiefly in response to nerve injury." (PMID 38785946, 2024). "Pre-clinical and clinical studies have observed that brain-derived neurotrophic factor (BDNF) level is enhanced following traumatic brain injury, possibly involving fracture healing." (PMID 38534361, 2024). "Elevated levels of BDNF are detected up to 30 days following neonatal HI injury, and pre‐treatment with intraventricular BDNF ameliorated HI brain injury and improved spatial learning and memory in P7 rats." (PMID 36636750, 2023). "The NF-kB/BDNF signaling pathway has been shown to be crucial for intact CST sprouting following brain injury." (PMID 33832542, 2021). "In animals, BDNF and its tropomyosin receptor kinase B receptor were shown to be increased in models of bladder inflammation and nerve injury." (PMID 33614695, 2021). "Our observations demonstrated that even in the case of patients with mild head trauma, the growth of plasma BDNF concentration was statistically significant in comparison to the control group." (PMID 32987792, 2020). "BDNF is reported as one of prominent target-derived trophic factor, of which administration protects RGCs from their death after nerve injury." (PMID 32127528, 2020).
injury (continued). "Within the whole group of children with mild head trauma, a statistically significant increase of IL-8 and BDNF concentration in comparison to the control group was observed." (PMID 32987792, 2020). "It has been reported that BDNF exerts vigorous effect on ischemic tissue and presents a promising approach to enhance the neurofunctional recovery after brain injury." (PMID 29765502, 2018). "In that study we demonstrated that TrkB-signaling is necessary for behavioral sensitization after nerve injury, which agreed with many other studies that applied BDNF peripherally or administered intrathecal BDNF or TrkB scavengers." (PMID 30627644, 2018). "In particular, there is a paucity of research on the effects of HIIT on markers related to brain injury, with only a single published report of elevations in serum brain-derived neurotrophic factor (BDNF) acutely after exercise." (PMID 30323770, 2018). "BDNF acts via its receptor TrkB and regulates neuroplasticity, and it is also upregulated following brain injury." (PMID 28122008, 2017). "Here we have demonstrated that presynaptic inhibition is required for setting the pain sensitivity under physiological condition and its regulation by BDNF after nerve injury is essential for neuropathic pain initiation." (PMID 25354791, 2014). "In animals, ω-3 PUFA supplementation provided protection against reduced plasticity and normalized BDNF after traumatic brain injury, whereas diets deficient in ω-3 PUFA lowered BDNF brain levels." (PMID 25386150, 2014). "BDNF is a protein essential for the differentiation, growth, and repair of neural networks following nerve injury and is a key modulator of functional expression in pain networks." (PMID 23208699, 2013). "Furthermore, another study has shown that ALC promotes the restoration of BDNF levels in the brains of rats with brain injury, demonstrating its neuroprotective effects." (PMID 40807441, 2025). "SCFAs (acetate, propionate, butyrate) are key microbiota-derived signals that inhibit HDACs, promote oligodendrocyte differentiation/myelination, preserve BBB integrity, and enhance neurotrophins (e.g., BDNF), collectively mitigating preterm-related brain injury." (PMID 41011544, 2025). "BDNF is a crucial mediator of synaptic plasticity, learning, and memory, and its upregulation is thought to facilitate neural repair and functional reorganization after brain injury." (PMID 40904820, 2025). "For example, in children with severe traumatic brain injury, correlational links between serum neural marker contents and assessments on the Glasgow scale were revealed for BDNF, and serum BDNF levels were normal in cases with favorable traumatic brain injury outcomes." (PMID 38203674, 2023). "Given that upregulation of BDNF and NGF in the dorsal horn after nerve injury is associated with an enhanced pro-inflammatory response and hyperalgesia, these findings are indicative of a normalization of neurotrophic levels in response to exercise, resulting in an anti-inflammatory response." (PMID 37138291, 2023). "Therefore, we analyzed the relationship between the SIRT1-mediated BDNF–TrkB signaling pathway and fluorosis brain injury, learning and memory, and provide new ideas and a theoretical basis for preventing and treating fluorosis brain injury." (PMID 37711250, 2023). "Since BDNF plays a critical role in brain health, it may be beneficial for BDNF to be up-regulated following brain injury to enhance recovery." (PMID 37626975, 2023). "However, another study reported that Nrf2 activation was regulated by the TrkB-BDNF pathway and the Nrf2 antioxidant axis was upregulated by BDNF overexpression in a rat model of traumatic brain injury." (PMID 31293390, 2019). "In view of the role of the BDNF-TrkB signaling in neuronal survival, targeting the BDNF-TrkB system may be a therapeutic strategy to reduce ICH-induced brain injury." (PMID 31307481, 2019).